SP1 (Sp1 transcription factor)
Diseases named in the same sentence as SP1 in open-access papers (continued):
Sharing a sentence is not in itself a finding about the gene and the disease.
tumor (continued). "Moreover, our in vivo results were consistent with the findings in vitro, confirming the suppressive effects of SS on HCC HepG2 tumor growth and regulations of CCAT1, miR-375-3p, SP1, and IRF5 expressions." (PMID 31681610, 2019). "Sp1 is involved in negative feedback loops with miRNAs, like miR-29b and miR-22, both acting as tumor suppressors in MM." (PMID 31315220, 2019). "Moreover, the IL-1α gene has been reported to be regulated by sp1 suggesting a feed-forward relationship between IL-1α and sp1 which would ultimately promote EGFR signaling and tumor progression." (PMID 31320902, 2019). "Mithramycin A (MTM) is a gene selective specificity protein 1 (Sp1) inhibitor that is employed as a chemotherapeutic agent that inhibits tumor cell growth without affecting normal cells." (PMID 32009938, 2019). "Moreover, SP1 is also found highly expressed in CRC and correlated with tumor metastasis and poor prognosis." (PMID 30474556, 2018). "Furthermore, the regulatory mechanism of MMP-9 in GE-treated cells was investigated because the migration and invasion of tumor cells is connected with MMP-9 expression through the control of transcription factors AP-1, Sp-1, and NF-κB." (PMID 28187175, 2017). "For instance, SP1 and KLF6 are known tumor suppressors in colorectal cancer." (PMID 28684851, 2017). "Importantly, knockdown of Sp1 or NF-κB (p65) and inhibition of the NF-κB signaling pathway using CAPE phenocopied the effects of miR-145-5p overexpression on the respective tumor cell phenotypes." (PMID 28832500, 2017). "An alteration in the levels of Sp1 and Sp3 could link MAOB and HiF-1α levels to tumor grade and aggressiveness." (PMID 26689994, 2016). "In this study using bioinformatic technology, we found that IL-6R, SOS-1, NF-IL-6, c-Fos, MAP3K10, NIK, SP1, MEF2, and other inflammatory factors and tumor regulatory molecules are also potential target genes of miRNA-155, but no definitive results have been reported yet." (PMID 27462776, 2016). "miR-22 acts as a tumor suppressor and induces cellular senescence by regulating cyclin-dependent kinase inhibitor 1A (CDKN1A), cyclin-dependent kinase 6 (CDK6), sirtuin 1 (SIRT1), and specificity protein 1 (Sp1)." (PMID 26927063, 2016). "Sp1 levels decrease with age in rodents and humans and several studies show that Sp1 levels are high in tumor vs. non-tumor tissue." (PMID 26967243, 2016). "In conclusion, our results demonstrate that miR-630, which could be transcriptionally reduced by the TGF-β-Erk/SP1 and JNK/c-Jun axis, functions as a tumor suppressor by targeting Slug and subsequently suppressing metastasis in HCC." (PMID 26993767, 2016). "We found that cZNF292 silencing decreased the transcriptional activity of E2F1, NF-κB, Sp1, HIF-1, AP-1, STAT3, and STAT5 in the U87MG and U251 cell lines, suggesting that cZNF292 silencing represses tumor tube formation through altering transcription factor activity." (PMID 27613831, 2016). "Importantly, in comparing the exposure of K562 single tumor cell to DOX alone or plus BORT formulations, the combined Tf-L-BORT and DOX resulted in the most downregulation of BCR/ABL and Sp1." (PMID 27144331, 2016). "These functional and quantitative genomic data coupled with the high expression of Sp transcription factors in tumor vs. non-tumor tissue suggests that Sp1, Sp3 and Sp4 are NOA genes and attractive drug targets." (PMID 26967243, 2016).
tumor (continued). "However, a single CpG site located at the junction of the two Sp1/Sp3 binding sites had moderate methylation, and the methylation values were significantly inversely correlated with the expression of CMTM3 in tumor tissues." (PMID 24586462, 2014). "In addition, the UPR-induced gene interactome interfaces with tumor-critical transcription factors such as FOS, HIFA, and SP1, as well as with members of the TGFβ family." (PMID 24039668, 2013). "Sp1, the Sp family transcription factor binds to GC-rich sequences including GC-boxes 5′-(G/T)GGGCGG(G/A)(G/A)(C/T)-3′ and plays a major role in cell growth and tumor progression by regulating many cell cycle specific genes." (PMID 23112860, 2012). "Based on these findings, we initially hypothesized that Sp1 might play a positive role in USP22 gene transcription, since USP22 is up-regulated in most human tumor cells." (PMID 23300749, 2012). "SP1 cooperates with other prominent transcription factors including oncogenes such as MYC, which may contribute to tumor cell proliferation and growth." (PMID 20576088, 2010). "Based on the ability of TMP to inhibit the growth of certain tumor-derived cell lines, and its effects on Sp1, its effect on the growth of RAW 264.7 cells was not surprising." (PMID 19133137, 2009). "In this study, we investigated whether Sp1 transcription factor induces ADAM17 and/or contributes to tumor cell invasiveness in hypoxia." (PMID 19772640, 2009). "Furthermore, SP13 is more prevalent in PVTT compared to tumours, whereas SP1 is more prevalent in adjacent non-tumour tissues compared to PVTT." (PMID 41543530, 2026). "We noticed that knockdown of SP1 in CRC cells resulted in decreased expression of multiple YAP direct target genes, which prompted us to explore whether SP1 cooperates with YAP/TEAD complex to promote tumorigenesis and tumor progression in CRC." (PMID 39875519, 2025). "In contrast, the expression level of SP1 was significantly greater in malignant cells than in normal cells (in‐house data: p = 0.005, GSE103322: p = 0.033, GSE181919: p = 0.025) and was greater in tumor samples of advanced‐stage HNSCC (in‐house data: p = 0.005)." (PMID 40056047, 2025). "Sp1 is clearly a negative prognostic factor for multiple cancers, and this is accompanied by increased expression of Sp transcription factors in tumors compared to non-tumor tissues." (PMID 36982239, 2023). "Therefore, blocking of SP1 or Rag GTPases failed to activate the mTORC1 pathway and inhibited tumor proliferation." (PMID 37532694, 2023). "In addition, we found that SNHG4 could be a potential therapeutic strategy given its mechanistic role in promoting tumor invasion, cell proliferation, and colony formation by regulating EMT and SP-1 signaling pathways." (PMID 37189636, 2023). "Interestingly, CDK6, another target of the hsa-miR-29a miRNA, was found to mediate the recruitment of the transcription factors c-Jun and Sp1 to the MMP2 promoter that positively enriched the angiogenic and fibrotic tumor microenvironment, as widely observed in TNBC (ER−) patient tissues." (PMID 36834918, 2023). "Further supporting a tumor-suppressor role for miR-22, oncogenes such as galectin-1 (LGALS1), ezrin (EZR), histone deacetylase 4 (HDAC4) tyrosine 3-monooxygenase/tryptophan 5-monooxygenase (YWHAZ), specificity protein 1 (SP1), and basigin (CD147) were reported to be hepatic targets of miR-22." (PMID 36139435, 2022). "However, hypoxia occurs during NSCLC tumor growth, and we found that hypoxia of NSCLC cells induced HIF1α competitive binding to SP1; this may relieve the SP1-Alu feedback suppression loop and increase circ-0001875 circularization." (PMID 35473752, 2022). "Sp1, a well-known TF ubiquitously expressed in mammalian cells, binds to, and acts through, GC boxes on the promoter of multiple target genes lacking a TATA box, which are involved in several fundamental cellular functions, including a number of tumor suppressors." (PMID 33898425, 2021).
tumor (continued). "Among the 108 patients with tumor metastasis, 56 patients (51.8%) had high expression of both HIF-1α and SP1, 12 patients (11.1%) had high expression of HIF-1α, 13 patients (12.0%) had high expression of SP1, and 27 patients (25.0%) patients had low expression of both HIF-1α and SP1." (PMID 31892989, 2020). "Moreover, the upregulation of P14ARF could generate activation or interaction with other factors such as Sp1, c-Jun, AP-1, and JNK that cooperate to prevent tumor-induced microthrombosis through activation of the anticoagulant factor TFPI-2." (PMID 32982771, 2020). "In addition, our microarray and bioinformatic analysis demonstrated that USP39 regulated diverse cellular signaling pathways that were involved in tumor biology, and several pivotal genes (IRF1, Caspase 8, and SP1) have been validated by quantitative real-time polymerase chain reaction." (PMID 30898977, 2019). "Further analysis showed that there was a negative correlation between SP1 mRNA and hsa-mir-149-5p in tumor tissues and adjacent normal tissues, suggesting that hsa-mir-149-5p may inhibit the occurrence of TSCC by inhibiting the expression of SP1." (PMID 31270251, 2019). "Therefore, we hypothesized that, by cooperating with Sp1, ZEB2 drives diverse cellular functions other than EMT and tumor invasiveness during tumor progression." (PMID 29416649, 2018). "In addition, we found that SP1 and vascular endothelial growth factors (VEGF) were decreased in DIRAS3-BGC-823 cells, suggesting that DIRAS3 expression may inhibit tumor growth by inhibiting angiogenesis." (PMID 30043279, 2018). "In ccRCC, a potential tumor suppressor function of KIBRA might be absent even in the presence of high SP1 expression levels if KIBRA promoter regions are deactivated by methylation." (PMID 29046731, 2017). "Thus, the oncogenic-like activity of Sp1, Sp3 and Sp4 and Sp-regulated genes coupled with their overexpression in tumor vs. non-tumor tissue suggests that Sp1, Sp3 and Sp4 are non-oncogene addiction (NOA) genes that are “attractive drug targets”." (PMID 26967243, 2016). "Moreover, several studies report that high expression of Sp1 and, in some cases, Sp3 in tumor vs. non-tumor tissue are negative prognostic factors for patients with pancreatic, glioma, colon, gastric, head and neck, prostate, lung and breast cancers." (PMID 26967243, 2016). "We previously demonstrated that NEU3 is up-regulated in tumor compared with that in adjacent non-tumor tissues in colon, renal, prostate and ovarian cancers, which may be regulated by Sp1/Sp3 transcriptional factors." (PMID 25803810, 2015). "In addition, Sp1 was present in some infiltrating lymphocytes of both the non-tumor and tumor regions of NPC patients." (PMID 25099028, 2014). "Furthermore, both Sp1 and YY1 expression levels correlate with KIF14 mRNA expression in primary serous OvCa tumors, demonstrating their potential role in maintaining high KIF14 levels in OvCa tumor cells." (PMID 24626475, 2014). "Furthermore, miR-22 suppresses tumor proliferation, tumorigenesis, and metastasis by targeting proteins, including Protein Kinase C Inhibitor Protein-1 YWHAZ, cluster of differentiation 147 (CD147), galectin-1 (LGALS1), cyclin A2 (CCNA2), and specificity protein 1 (SP1)." (PMID 39953622, 2025). "Similarly, inhibition of SP1 with mithramycin decreased the tumour burden, which could not be compensated by co-implantation with the CAFs." (PMID 38429478, 2024). "Therefore, SP1 (or YY1) may directly interact with the promoter region of lncRNA AFAP1-AS1 as upstream transcription factors, thereby regulating the expression of lncRNA AFAP1-AS1 and promoting or inhibiting tumor progression." (PMID 37686205, 2023).
tumor (continued). "Thus, we wondered whether Sp1 can be conjugated with SUMO2/3 and be a substrate of SENP3, as we have previously shown that the protein level of SENP3, a SUMO2/3 specific protease, is increased in tumor tissues and under various stress conditions." (PMID 26511642, 2016). "However, neither Sp1 nor COX2 was correlated with tumor stage, lymphovascular invasion, and other clinicopathological factors, which may partially be explained by the small sample size of our study." (PMID 27057636, 2016). "Conversely, in the absence of HER2-signaling-phosphorylated Sp1, HDACs tend to combine with S100 and upregulate the expression of FAS and MIR146A genes, contributing to tumor suppression." (PMID 37174034, 2023). "Notably, high NR2E3 expression emerged as a critical determinant correlated with favorable clinical outcomes, regardless of high expression levels of Sp1, β‐catenin, or p300, reinforcing NR2E3's role as a good prognostic indicator and tumor suppressor." (PMID 38790135, 2024). "Consequently, BALB/c nude mice were subcutaneously injected with SP1-depleted cells with or without exogenous overexpression of UBE2N and then monitored tumor growth in vivo." (PMID 36964266, 2023). "In tumor-bearing nude mice model, DHA significantly inhibited the growth of esophageal squamous cancer xenografts, and downregulated the expression of SP1 and hTERT protein, while no side effects were observed from heart, kidney, liver, and lung tissues by HE stain." (PMID 34744749, 2021). "To determine whether KIF14 overexpression in OvCa tumors could also be linked to transcriptional regulation, we measured mRNA expression of Sp1, YY1 and HSF1 in a subset of OvCa tumor tissues with (15 samples) and without (50 samples) KIF14 genomic gain." (PMID 24626475, 2014).
infection (62 papers, 2007 to 2025). The state of being infected such as from the introduction of a foreign agent such as serum, vaccine, antigenic substance or organism. "By overexpression of Sp1 in hBMECs, we further observed that the infection-caused TGFBRII reduction was completely restored detected by Western blot and qPCR." (PMID 34281571, 2021). "While this bottleneck at early stages of S.Tm θ infection was predominantly sp22-mediated, at the highest CFU/g achieved by this strain (81,500 CFU/g), there was evidence of infection of macrophage (sp8 cells) as well as neutrophils (sp1, sp2, sp6)." (PMID 40462990, 2025). "During adenoviral infection, separate molecules of E1A bind to the STAT1 dimer and to CBP/p300, preventing the formation of the complex and displacing Sp1 protein to support infection." (PMID 40143226, 2025). "To elucidate how the altered binding affinity of SP1/SP3 at the 2SP site specifically enhances NRAMP1 promoter activity after H37Ra infection, we aimed to investigate the roles of SP1 and SP3 in this process." (PMID 40362465, 2025). "ChIP-Seq showed largely matching Sp1 and Pol II binding to most IE and E gene promoters 2 h post-infection (hpi)." (PMID 40143226, 2025). "The infection experiments demonstrated that the three S. phocae isolates Sp1, Sp16 and Sp55 were both adherent and invasive in all tested cell types." (PMID 38289941, 2024). "Accordingly, SP1 not only directly killed C. neoformans but also benefited the host immune system to clear C. neoformans during the infection." (PMID 36916981, 2023). "Some of these activators, such as NF-κB, ATF/CREB, and SP1, have been shown to be activated by infection (32, 64, –, 66)." (PMID 36645269, 2023). "FOXA1 and SP1 were also upregulated during infection in both Vero E6 and Calu-3 cells, but their overexpression was not sufficient to trigger ZDHHC20Long production in HeLa cells." (PMID 37952051, 2023). "The emergence of SP-1 mutants—“cheaters”—limits the success of acute infection and prevents transmission to and infection of new hosts." (PMID 34154400, 2021). "We next predicted the Sp1 that would act as the potential transcription factor targeting TGFBRII promotor, and both Western blot and qPCR data showed that Sp1 was also decreased in hBMECs along with RS218 infection." (PMID 34281571, 2021). "Accordingly, Cos-7 cells were transfected with siRNA targeting SP1, with scrambled siRNA, or only mock-treated and miRNA expression levels were analysed after infection with archetype, the two point-mutant derivatives sp1-2 and sp1-4; and the Dunlop strain." (PMID 30200237, 2018). "For example, infection with CMV results in up-regulation of Sp1 activity, which induces NF-κB activation." (PMID 26814140, 2016). "In line with this, knockdown of Sp1 prior to infection prevented HCV-mediated up-regulation of NRG1 expression suggesting that HCV Sp1-dependently mediates increased production of NRG1." (PMID 26886748, 2016). "In a previous investigation, we found that AP-1 (together with Sp1) was activated in host cells upon infection with human cytomegalovirus and that a single artesunate treatment suppressed AP-1 activation and production of virus-specific proteins in host cells." (PMID 21637790, 2011). "Next, we aimed to determine whether the altered SP1/SP3 binding affinity at the 2SP site was a contributing factor to the changes in bovine NRAMP1 promoter activity after H37Ra infection." (PMID 40362465, 2025).